AFDN-DT (AFDN divergent transcript)
Synonyms: HGC6.4; dJ431P23.3; XBP1SBM; C6orf123; HGC6.2; LINC01557; dJ431P23.4; LINC01558; formerly AFDN-AS1; C6orf124; MLLT4-AS1
Gene: Long non-coding RNA gene on chromosome 6 (167,781,478 to 167,827,561, reverse strand). Ensembl gene ENSG00000198221.
Diseases named in the same sentence as AFDN-DT in open-access papers:
AFDN-DT is named in the same sentence as 1 disease in open-access papers, as found by Europe PMC text mining. Sharing a sentence is not in itself a finding about the gene and the disease. The quoted sentences say what the papers report.
tumour (1 paper, 2020). "In the present study, we systematically investigated the function of AFDN‐DT in GC and demonstrated its role as a tumour suppressor through transcriptional regulation of the genes essential for malignant transformation." (PMID 31981317, 2020).